RASD2 (RASD family member 2)
Description:
GTPase signaling protein that binds to and hydrolyzes GTP. Regulates signaling pathways involving G protein-coupled receptor and heterotrimeric proteins such as GNB1, GNB2 and GNB3. May be involved in selected striatal competencies, mainly locomotor activity and motor coordination.
Synonyms: TEM2; Rhes; MGC:4834
Tractability: Antibody: UniProt places it where antibodies can reach, with medium confidence; its Gene Ontology location is reachable by antibodies, with medium confidence; the Human Protein Atlas places it where antibodies can reach.
Gene: Protein-coding gene on chromosome 22 (35,539,796 to 35,554,003, forward strand). Ensembl gene ENSG00000100302.
Subcellular location: Cell membrane
Subcellular location (Human Protein Atlas): Cytosol; Plasma membrane
Gene Ontology:
Molecular function: G-protein beta-subunit binding; GTPase activity; GTP binding
Biological process: locomotory behavior; positive regulation of phosphatidylinositol 3-kinase/protein kinase B signal transduction; positive regulation of protein sumoylation; signal transduction; synaptic transmission, dopaminergic
Cellular component: plasma membrane; synapse
Genetic constraint (gnomAD): Loss-of-function variants: 7 observed, 16.49 expected, observed/expected ratio (o/e) 0.42, 90% interval 0.24 to 0.8. The upper end of that interval is the gene's LOEUF score, 0.8, which puts it in group 3 of 6, group 1 being the genes least tolerant of losing a copy. Missense variants: 274 observed, 398.67 expected, observed/expected ratio (o/e) 0.69, 90% interval 0.62 to 0.76. Synonymous variants: 155 observed, 161.71 expected, observed/expected ratio (o/e) 0.96, 90% interval 0.84 to 1.1.
Homologues: Orthologues: chimpanzee RASD2 (100% identical), dog RASD2 (98% identical), rabbit RASD2 (98% identical), mouse Rasd2 (95% identical), rat Rasd2 (95% identical), guinea pig RASD2 (94% identical), macaque RASD2 (92% identical), tropical clawed frog rasd2 (86% identical). Paralogues in human: RASD1 (64% identical), DIRAS1 (32% identical), DIRAS2 (30% identical), RAP2A (28% identical), RAP2B (28% identical), RRAS2 (27% identical), RRAS (27% identical), RAP2C (27% identical), RAP1A (26% identical), RAP1B (26% identical), RIT1 (26% identical), KRAS (25% identical), and 23 more.
Diseases named in the same sentence as RASD2 in open-access papers:
RASD2 is named in the same sentence as 27 diseases in open-access papers, as found by Europe PMC text mining. Sharing a sentence is not in itself a finding about the gene and the disease. The quoted sentences say what the papers report.
schizophrenia (4 papers, 2013 to 2023). A major psychotic disorder characterized by abnormalities in the perception or expression of reality. "These analyses suggested that one or more miRNAs underlie the observed downregulation of RASD2 in schizophrenia patients." (PMID 35855328, 2022). "We previously reported that RASD2 is significantly downregulated in schizophrenia patients compared with healthy control subjects." (PMID 35855328, 2022). "The RPKM values for RASD2 in the schizophrenia group were significantly altered compared with those in the healthy controls group." (PMID 35855328, 2022). "Subsequent analysis of human blood samples verified that the expression of RASD2 was downregulated and that of miR-4763-3p, which targets RASD2, was upregulated in schizophrenia patients." (PMID 35855328, 2022). "Subsequently, qPCR analysis of blood samples revealed that RASD2 was significantly downregulated in the schizophrenia group compared with the control group." (PMID 35855328, 2022). "The results revealed a significant downregulation of RASD2 and upregulation of the miRNA miR-4763-3p in blood samples from schizophrenia patients." (PMID 35855328, 2022). "Functional enrichment analysis of the 61 schizophrenia-related DEGs we identified revealed that most are enriched in synaptic functioning and neurotransmitter-related signaling, and the ceRNA network indicated that RASD2 plays a key role in schizophrenia." (PMID 35855328, 2022). "Moreover, RASD2 was mainly enriched in the striatum of both healthy subjects and schizophrenia patients." (PMID 35855328, 2022). "Moreover, post-mortem analysis of the prefrontal lobe of schizophrenia patients revealed downregulated expression of RASD2." (PMID 35855328, 2022). "We also demonstrated that miR-4763-3p significantly inhibits RASD2 function and thus itself may prove efficacious for the treatment of schizophrenia." (PMID 35855328, 2022). "Our findings demonstrate that miR-4763-3p may target RASD2 mRNA and thus may serve as a potential biomarker and therapeutic target for schizophrenia, providing a theoretical foundation for further studies of the molecular basis of this disease." (PMID 35855328, 2022). "Indeed, analysis of blood samples confirmed that RASD2 is downregulated in schizophrenia patients." (PMID 35855328, 2022). "Therefore, we can infer that RASD2 may indirectly affect signal transduction in the central nervous system—and hence the symptoms of schizophrenia—through endocrine function." (PMID 35855328, 2022). "Besides, the interaction between DAO and RASD2 has provided an insight in integrating the glutamate and dopamine hypotheses of schizophrenia." (PMID 23555897, 2013). "Using candidate-gene positional cloning approach we have finely mapped genes vulnerable to schizophrenia in Taiwan, including DISC1 at chromosome 1q42, RASD2 and CACNG2 at chromosome 22q12, and DPYSL2, TRIM35 and PTK2B at chromosome 8p21 (in preparation)." (PMID 23555897, 2013). "Between-gene interactions including DAO*DISC1,DAO*NRG1 and DAO*RASD2 and a within-gene interaction for CACNG2 were found among schizophrenia subjects with severe sustained attention deficits, suggesting a modifying effect of impaired neuropsychological functioning." (PMID 23555897, 2013).
Huntington disease (3 papers, 2013 to 2022). Huntington disease (HD) is a rare neurodegenerative disorder of the central nervous system characterized by unwanted choreatic movements, behavioral and psychiatric disturbances and dementia. "We finally screened five genes, including Arpp21, Rgs4, Rasd2, Gabrd, and Tmod1, two (Arpp21 and Rasd2) of which have been reported to be related with Huntington’s disease." (PMID 34433483, 2021).
depression (2 papers, 2023 to 2025). "Depression-like behaviors induced byovariectomy were associated with decreased RASD2 and DRD2 protein levels in thehippocampus, and Rasd2 overexpression in the hippocampus alleviateddepression-like behaviors and increased DRD2 expression." (PMID 36566472, 2023). "In summary, Rasd2 plays a role in depression-like behavior induced byovariectomy, and this role is related to the regulation of DRD2." (PMID 36566472, 2023). "RNA-seq, western blot,enzyme-linked immunosorbent assay, and co-immunoprecipitation were used to explore therole of Rasd2 in a depression model induced by ovariectomy and theantidepressant-like effects of 9-hour fasting." (PMID 36566472, 2023). "Rasd2 can therefore bepostulated to be a potential therapeutic target for depression and perhaps also a potentialpredictive marker for depression." (PMID 36566472, 2023). "Rasd2 regulatesDRD2-mediated antidepressant-like effects of acute fasting in ovariectomized mice.Rasd2 can therefore be postulated to be a potential therapeutictarget for depression and perhaps also a potential predictive marker for depression." (PMID 36566472, 2023). "Ras Homolog Enriched In Striatum (RASD2), a member of the Ras superfamily of small GTPases, was initially characterized by its abundant expression in striatal tissues and its involvement in neurological disorders, including epilepsy and depression." (PMID 40289764, 2025).
Parkinson disease (2 papers, 2022 to 2025). A progressive degenerative disorder of the central nervous system characterized by loss of dopamine producing neurons in the substantia nigra and the presence of Lewy bodies in the substantia nigra and locus coeruleus. "Of particular relevance to our study, research in Parkinson's disease unexpectedly revealed RASD2's influence on thyroid hormone homeostasis, suggesting potential endocrine regulatory functions." (PMID 40289764, 2025).
Allergy (1 paper, 2021). An allergy is an immune response or reaction to substances that are usually not harmful. "RASD2, IL24, CCL2 and CCL7 are immunologically relevant biomarkers in allergy." (PMID 33849432, 2021).
Alzheimer disease (1 paper, 2024). A progressive, neurodegenerative disease characterized by loss of function and death of nerve cells in several areas of the brain leading to loss of cognitive function such as memory and language. "Additionally, RASD2 could protect neurons by removing damaged mitochondria through mitophagy, playing an important role in diseases such as Alzheimer’s disease." (PMID 39609876, 2024).
autism (1 paper, 2024). Persistent deficits in social interaction and communication and interaction as well as a markedly restricted repertoire of activity and interest as well as repetitive patterns of behavior. "Single nucleotide polymorphism (SNP) of the Rhes gene, RASD2, s were found associated with schizophreniapatients, and a rare and conserved somatic mutation (R57H) was found in the RASD2 in twins diagnosed with autism." (PMID 38589732, 2024).
glioma (1 paper, 2025). A benign or malignant brain and spinal cord tumor that arises from glial cells (astrocytes, oligodendrocytes, ependymal cells). "Subsequent investigations have expanded RASD2's oncogenic portfolio, demonstrating its crucial role in tumor immune evasion in gliomas." (PMID 40289764, 2025). "Studies have demonstrated that elevated RASD2 expression correlates with unfavorable clinical outcomes in gastrointestinal stromal tumors and gliomas." (PMID 40289764, 2025).
lymph node metastasis (1 paper, 2025). "Importantly, elevated RASD2 expression strongly correlated with aggressive clinicopathological features, including lymph node metastasis, extrathyroidal extension, and advanced TNM staging." (PMID 40289764, 2025).
neuroblastoma (1 paper, 2023). Neuroblastoma (NB) is the most common solid, extracranial childhood tumor. "To assess the targeting efficiency of Rasd2 gRNAs, we transfected them along with a Cas9 plasmid into cultured mouse neuroblastoma cells (N2a)." (PMID 37637962, 2023).
thyroid cancer (1 paper, 2025). "While we demonstrate that RASD2 significantly influences glycolytic metabolism in thyroid cancer, the precise molecular mechanisms underlying this regulation remain to be fully elucidated." (PMID 40289764, 2025). "Our findings revealed that RASD2 promotes thyroid cancer progression through enhanced cellular proliferation, invasion, and glycolytic metabolism, while miR‐485‐5p acts as a tumor suppressor by directly targeting RASD2." (PMID 40289764, 2025). "Our investigation revealed that RASD2 functions as a key regulator of this metabolic phenotype in thyroid cancer." (PMID 40289764, 2025). "Building on these observations, our investigation provides the first comprehensive characterization of RASD2's role in thyroid cancer through complementary in vitro, in vivo, and clinical analyses." (PMID 40289764, 2025). "Our findings establish the miRNA‐485‐5p/RASD2 axis as a critical regulatory pathway in thyroid cancer progression, offering new insights into disease pathogenesis and potential therapeutic interventions." (PMID 40289764, 2025). "Immunohistochemical staining of a tissue microarray containing 96 paired thyroid cancer specimens and adjacent normal tissues demonstrated markedly increased RASD2 protein levels in tumor tissues." (PMID 40289764, 2025). "These initial observations led us to investigate the molecular mechanisms through which RASD2 promotes thyroid cancer progression, focusing particularly on its role in tumor growth, metastasis, and metabolic reprogramming." (PMID 40289764, 2025). "Correlation analysis demonstrated an inverse relationship between miR‐485‐5p and RASD2 expression levels in thyroid cancer tissues." (PMID 40289764, 2025). "These in vivo results provide compelling evidence that RASD2 plays a crucial role in promoting both primary tumor growth and metastatic colonization in thyroid cancer." (PMID 40289764, 2025). "In this study, we investigated the functional role of RASD2 and its regulation by miR‐485‐5p in thyroid cancer through comprehensive analyses of clinical specimens, cell lines, and animal models." (PMID 40289764, 2025). "Collectively, these findings establish miR‐485‐5p as a negative regulator of RASD2 in thyroid cancer, suggesting a potential tumor‐suppressive role for this miRNA." (PMID 40289764, 2025). "To elucidate the biological function of RASD2 in thyroid cancer, we examined RASD2 expression across multiple cell lines." (PMID 40289764, 2025). "To investigate the clinical relevance of RASD2 in thyroid cancer, we first analyzed RASD2 expression using the GEPIA database, which revealed significant upregulation in thyroid cancer tissues compared to normal controls." (PMID 40289764, 2025). "These molecular findings explain how miR‐485‐5p functions as a tumor suppressor in thyroid cancer through RASD2 regulation." (PMID 40289764, 2025). "To conclude, our study identifies RASD2 as a crucial driver of thyroid cancer progression and a potential prognostic biomarker." (PMID 40289764, 2025). "While the miR‐200 family has been shown to regulate RASD2 in podocyte differentiation, our investigation identifies miR‐485‐5p as a novel upstream regulator of RASD2 in thyroid cancer." (PMID 40289764, 2025). "RASD2 showed significant upregulation in thyroid cancer tissues, with elevated expression correlating with adverse clinicopathological parameters including lymphatic metastasis, extrathyroidal invasion, and advanced TNM stage." (PMID 40289764, 2025). "This study investigates the role of RASD2 (Ras Homolog Enriched In Striatum) in thyroid carcinoma progression and its modulation by microRNA‐485‐5p." (PMID 40289764, 2025). "Through integrated analysis of published datasets, coupled with extensive cellular studies across multiple thyroid cancer cell lines, we demonstrated consistent RASD2 upregulation in both primary thyroid cancer tissues and malignant cell lines compared to their normal counterparts." (PMID 40289764, 2025).
thyroid cancer (continued). "However, the functional significance of RASD2 in thyroid cancer pathogenesis remains largely unexplored, warranting comprehensive investigation." (PMID 40289764, 2025). "Notably, this miR‐485‐5p/RASD2 axis is dysregulated in thyroid cancer, with diminished miR‐485‐5p expression leading to RASD2 upregulation." (PMID 40289764, 2025). "While we focused on RASD2 as a target of miRNA‐485‐5p, future studies should investigate other downstream targets of miRNA‐485‐5p that may also contribute to thyroid cancer progression, providing a more complete understanding of miRNA‐485‐5p's role in this disease." (PMID 40289764, 2025). "Additionally, although we establish miR‐485‐5p as a direct regulator of RASD2, other potential upstream regulators may contribute to RASD2 dysregulation in thyroid cancer." (PMID 40289764, 2025). "Furthermore, comparative studies between RASD2 silencing and established glycolysis inhibitors would help position RASD2‐targeted therapy within the broader landscape of metabolic interventions in thyroid cancer." (PMID 40289764, 2025). "Western blot analysis of thyroid cancer cell lines (BCPAP, IHH4, KTC, and TPC‐1) demonstrated increased RASD2 expression compared to the normal human thyroid epithelial cell line, Nthy‐ori 3‐1." (PMID 40289764, 2025).
uveal melanoma (1 paper, 2023). A melanoma derived from melanocytes of the uveal tract. "RASD2 encodes a Ras-related GTP-binding protein and involves in the development and metastasis of Uveal melanoma." (PMID 36681855, 2023).
viral infection (1 paper, 2025). "Notably, the mRNA and protein levels of these genes significantly increase following viral infection, with both Ifit2 and Rasd2 exhibiting upregulation across various coronavirus infections." (PMID 40547011, 2025).
tumor (2 papers, 2016 to 2025). "The functional significance of this upregulation was confirmed through loss‐of‐function studies, where RASD2 knockdown significantly impaired tumor cell proliferation and invasion, and attenuated both tumor growth and metastatic potential in xenograft models." (PMID 40289764, 2025). "Immunohistochemical and immunoblotting examination of harvested tumor tissues demonstrated markedly decreased Ki‐67 proliferation marker and RASD2 expression in the knockdown group." (PMID 40289764, 2025). "Mechanistically, we identified miRNA‐485‐5p as a crucial negative regulator of RASD2, whose overexpression recapitulated the tumor‐suppressive effects of RASD2 knockdown." (PMID 40289764, 2025). "Monitoring of tumor development revealed that RASD2 silencing substantially reduced both tumor growth rates and final tumor masses compared to sh‐NC controls." (PMID 40289764, 2025). "In vivo studies further validated the therapeutic potential of RASD2 inhibition, demonstrating reduced tumor growth and metastatic burden." (PMID 40289764, 2025). "Animals receiving sh‐RASD2‐transfected cells developed fewer lung metastases compared to those injected with sh‐NC control cells, with confirmed RASD2 downregulation in sh‐RASD2 tumor samples." (PMID 40289764, 2025).
RASD2 also shares sentences with these, for which no sentence is quoted: infection (4 papers); Anxiety (3); asthma (1); cancer (1); chronic obstructive pulmonary disease (1); colorectal cancer (1); epilepsy (1); gout (1); idiopathic pulmonary fibrosis (1); neurological disorders (1); Obesity (1); psychiatric disorder (1); thyroid disease (1).